S100A8 (S100 calcium binding protein A8)
Diseases named in the same sentence as S100A8 in open-access papers (continued):
Sharing a sentence is not in itself a finding about the gene and the disease.
autoimmune disease (continued). "Expressed strongly by myeloid cells, damage-associated molecular pattern (DAMP) proteins S100A8 and S100A9 are found in the serum of patients with infectious and autoimmune diseases." (PMID 31437241, 2019). "In a mouse model of autoimmune disease autoreactive CD8+ T cells were induced after the local release of S100A8/A9, resulting in the development of systemic autoimmunity." (PMID 22489132, 2012). "S100A8 and S100A9 expression levels increased in many types of cancer, neurodegenerative disorders, inflammatory and autoimmune diseases and they are implicated in the numerous disease pathologies." (PMID 22489132, 2012). "Paquinimod may have potential therapeutic applications as an S100A8/S100A9 inhibitor, as excessive release of S100A8/S100A9 is associated with the occurrence and development of various inflammatory and autoimmune disorders." (PMID 41476978, 2025). "Moreover, we examine the interactive feedback mechanisms among NLRP3 inflammasome, S100A8/A9, and Gasdermin D, exploring their implications in autoimmune diseases." (PMID 40948742, 2025). "In addition, extracellular S100A8/A9 is a well-established biomarker for many acute and chronic inflammatory disorders, including cardiovascular diseases, autoimmune diseases, and infections." (PMID 39699020, 2024). "Furthermore, the upregulation of S100A8 and S100A8/A9 proteins in peripheral blood B cells was rarely detected in patients with other autoimmune diseases." (PMID 37165399, 2023). "The S100A8/S100A9 complex is the most abundant DAMP in many autoimmune diseases." (PMID 32075957, 2020). "The S100A8/A9-TLR4 interaction has also been shown to be involved in the pathogenesis of systemic infections and autoimmune diseases." (PMID 41155408, 2025). "S100A8 and S100A9 which are mainly expressed in myeloid cells naturally form a stable heterodimer and involve in inflammatory processes that lead to autoimmune diseases and many human cancers." (PMID 33294444, 2020). "S100A8/A9 (calprotectin) and S100A12 proinflammatory mediators are found at inflammatory sites and in the serum of patients with inflammatory or autoimmune diseases." (PMID 27057553, 2015). "The S100A8/A9-TLR4 interaction has been shown to be involved in the pathogenesis of systemic infections, autoimmune diseases, malignancy, and acute coronary syndrome." (PMID 24453429, 2013). "S100A8 and S100A9 levels are markedly increased in a wide range of inflammatory conditions, including autoimmune diseases, cancers, and neurodegenerative disorders, and they may serve as effective biomarkers for disease detection and prognosis." (PMID 40948742, 2025). "Even if encouraging results have been obtained with S100A8/A9 blockers for treating autoimmune disease and cancer, their use in preeclampsia has not yet been validated." (PMID 41155408, 2025). "Thus, elevated S100A8/A9 and S100A12 levels serve as activity biomarkers of diverse autoimmune diseases." (PMID 34783307, 2021). "Human clinical studies have already established a link between S100A8 and S100A9 and autoimmune-related arthritic diseases, suggesting that the spontaneous spondyloarthritis observed in crab-eating macaques may be related to autoimmune diseases." (PMID 39877611, 2025). "Although this post-translational form of S100A9 could be a determinant player for the development of chronic and autoimmune diseases, the presence of S100A8/A9-P in clinical samples has not yet been investigated to support this assumption." (PMID 31739406, 2019). "However, treatments with nontoxic doses of S100A8/A9 blockers have demonstrated encouraging results in experimental and clinical interventional studies on autoimmune disease and cancer, suggesting that complete systemic S100A8/A9 inhibition is probably not required for therapeutic effect." (PMID 24453429, 2013).
Arthritis (38 papers, 2009 to 2025). Inflammation of a joint. "In contrast, no change in TDS was observed in the S100a9−/− mice with SCW arthritis, underlining the role of S100A8/9 in pain perception." (PMID 32854769, 2020). "Studies have implicated S100A8 and S100A9 in the initiation and progression of immunoinflammatory diseases, including autoimmune synovitis, Sjögren’s syndrome, arthritis, systemic sclerosis and systemic lupus erythematosus." (PMID 40346703, 2025). "Data obtained from studies with RA patients revealed that systemic and synovial expression levels of S100A8/A9 correlated with joint inflammation and damage in arthritis." (PMID 40358151, 2025). "Murine arthritis models have also demonstrated that blocking S100A8/A9 can ameliorate inflammatory processes, suggesting the potential for targeting S100 proteins in human arthritis patients." (PMID 38612896, 2024). "Our data suggest that monocytes/macrophages are one of the major immune cells responsible for S100a8/a9 release in the Pam2CSK4-induced arthritis model." (PMID 37396347, 2023). "Accordingly, GSK-J4 treatment of our ER-Hoxb8 monocytes reduced expression of the proinflammatory alarmins S100a8 and S100a9, which have been shown to drive the inflammatory process of arthritis." (PMID 35543413, 2022). "High levels of both the alarmin S100A8/A9 and the pro-inflammatory cytokine IL-1β are found in many patients suffering from various forms of arthritis." (PMID 34412663, 2021). "Levels of the alarmin S100A8/A9 and interleukin (IL)-1β are both increased in arthritis patients and correlate with disease activity and progression of tissue erosion." (PMID 34412663, 2021). "We previously presented S100A8/A9 as a good biomarker for joint inflammation and arthritis pathology under circumstances of high IL-1 signaling in mice that lack the gene encoding IL-1 receptor antagonist (Il1rn−/− mice)." (PMID 34412663, 2021). "Preclinical models in mice have also confirmed a functional role of S100A8/S100A9 in the process of arthritis and autoimmunity." (PMID 30828327, 2019). "Injection of anti-S100A8 IgG increased the arthritis score, indicating that extracellular S100A8 provides some protection against chronic inflammation." (PMID 31437241, 2019). "S100A8 has been shown to promote the commitment of hematopoietic stem cells and progenitor cells to myelogenesis in experimental arthritis." (PMID 31437241, 2019). "There is a synergetic effect between TNF, IL-1ß, IL-17, and S100A8 leading to induction of erosive MMPs and exaggeration of cartilage erosion during arthritis." (PMID 30828327, 2019). "Functional relevance of S100A8/S100A9 expression was further confirmed by analysis of experimental models of arthritis and synovial inflammation in S100A9−/− mice." (PMID 30828327, 2019). "This led to arthritis in respectively 60% and 95% of WT and S100a8-/- mice, the latter developing more severe disease, with a mean score of 8.3 ± 1.1 on day 35, compared to 5.7 ± 1.3 for WT." (PMID 31437241, 2019). "Neutrophils stimulated with LPS release S100A8 at low concentrations (10−10 M), and the concentrations found in the plasma of patients with arthritis (10−11 M) are consistent with its chemotactic activity." (PMID 31437241, 2019). "It has also been confirmed that S100A8/A9 contributes to cartilage degradation and development of inflammatory arthritis in an antigen-induced arthritis model." (PMID 29379499, 2017). "In a mouse model of collagenase-induced arthritis, the expression of S100A8 and S100A9 in synovial was upregulated in wild-type mice." (PMID 29379499, 2017). "Serum levels of S100A8/A9 have been found to correlate with radiographic features of arthritis in PsA, and were predictive of progression of radiographic damage of the spine and syndesmophyte formation in AS." (PMID 27776554, 2016).
Arthritis (continued). "Higher levels of S100A8/9 levels have been correlated with disease progression in patients’ with early osteoarthritis, and has been reported to be an important mediator of pain response during the acute phase of inflammation in arthritis mouse models." (PMID 40215752, 2025). "Overall, our data suggest that S100a8/a9 might be used as a biomarker to predict septic arthritis before the debut of clinical arthritis symptoms in a systemic S. aureus infection." (PMID 37396347, 2023). "Importantly, S100a8 and S100a9 were the top genes that distinguished the arthritis mice and non-arthritis mice on the day after infection." (PMID 37396347, 2023). "Serum S100A8 levels differed according to fever and central nervous system (CNS) involvement (p < 0.001 and p = 0.049, respectively), and urine and salivary S100A8 showed significant differences in arthritis and malar rash, respectively (p = 0.038 and p = 0.018, respectively)." (PMID 35529863, 2022). "Moreover, in a seronegative experimental arthritis model, local S100A8 was monitored in vivo with optical imaging using anti-S100A8-Cy7 tracers." (PMID 35741108, 2022). "Uncontrolled activity of S100A8/A9 alarmins drives TNF-induced arthritis in mice." (PMID 35543413, 2022). "TLR4 has been shown to promote osteoclast-mediated bone erosion during arthritis through the detection of neutrophil-derived S100A8/A9, presenting the possibility that TLR4 plays a role in osteomyelitis, even in those cases triggered by Gram-positive pathogens." (PMID 36226943, 2022). "A possible second mechanism to explain our findings is that, like S100A8/A9, other factors that are present during arthritis development can induce IL-1β expression and regulate its activation and as such be sufficient to fully activate IL-1β in Il1rn−/−XS100a9−/− mice." (PMID 34412663, 2021). "S100A8/9 serum high concentrations can be found neither in other forms of arthritis nor in other causes of FUO." (PMID 34768386, 2021). "First, we determined whether in the acute synovitis model of SCW induced arthritis in C57Bl/6 mice, S100A8 or S100A9 genes and proteins were expressed." (PMID 32854769, 2020). "In fact, S100A8 has been shown to inhibit mast cell activation, scavenge ROS and decrease arthritis symptoms and thus may be considered a potent anti-inflammatory factor." (PMID 31437241, 2019). "However, data on the distribution of the S100A8 homodimer are scarce, and before investigating its possible role in arthritis, we first sought to determine if it is even present in association with the disease." (PMID 31437241, 2019). "Further, S100A8 produced by activated macrophages is also known to stimulate osteoclast differentiation and osteoclast function at the site of inflammation in experimental arthritis." (PMID 27599571, 2016). "In this study, we explore the biomarker potential of S100A8/A9 in interleukin-1 receptor antagonist deficient (IL-1Ra–/–) mice, a non-immune complex-mediated arthritis model." (PMID 27776554, 2016). "Additionally, S100A8/A9 is selectively released from early infiltrating phagocytes, thereby reflecting a local first-line response of the innate immune system in arthritis development." (PMID 27776554, 2016). "In particular it has been shown that, S100A8 homodimers could promote chondrocyte-mediated cartilage destruction, upon metalloproteinase activation, in experimental arthritis." (PMID 23626736, 2013). "Indeed, S100A9−/− mice, which also lack the S100A8 protein, show reduced bone erosion in antigen-induced arthritis through a mechanism partly related to a decrease in osteoclasts." (PMID 23029038, 2012). "Furthermore, we also found the most pronounced increased serum concentrations of S100A8/A9 in patients with arthritis (P = 0.016), as was previously reported, as well as in patients with kidney involvement (P = 0.026)." (PMID 21492422, 2011).
Arthritis (continued). "Furthermore, in mice with experimentally induced arthritis, serum levels of S100A8/A9 were significantly increased and correlated with macroscopic joint swelling and histological inflammation, while serum levels of pro-inflammatory cytokines did not correlate with joint swelling." (PMID 37372165, 2023). "Synovitis during RA is characterized by a high abundance of neutrophils and macrophages expressing S100A8 and S100A9 especially at the cartilage–pannus junctions indicating that S100-expression is closely associated with cartilage destruction and bone erosion in arthritis." (PMID 30828327, 2019). "The combined effect of S100A8, TNF‐α, IL‐1β and IL‐17 induced activated matrix metalloproteinases and exacerbated arthritis." (PMID 37132178, 2023). "Beyond that, S100A8 and S100A9 are known key players in the pathogenesis of arthritis in murine models." (PMID 35543413, 2022). "The results showed that the expression levels of S100A9, S100A8, and MMP8 in rats with arthritis pain were visibly lower than the Sham group." (PMID 34803684, 2021). "The identification of S100A9, S100A8, and MMP8 genes can provide new therapeutic targets for arthritis pain and affect the signaling pathway to play an anti-inflammatory role after the treatment of BoNT/A." (PMID 34803684, 2021). "Studies showed that two members of the S100 family, S100A8 and S100A9, are overexpressed at local sites of inflammation, which have been proven to be useful genes of inflammatory diseases such as arthritis, bowel disease, and chronic inflammatory lung." (PMID 34803684, 2021). "We found that the mRNA expression levels of S100A9, S100A8, and MMP8 were significantly decreased after CFA-induced arthritis pain, while BoNT/A increased the expression changes of these genes." (PMID 34803684, 2021). "S100-alarmins, especially S100A8/S100A9, are highly upregulated in different forms of arthritis and autoimmune diseases in children." (PMID 30828327, 2019). "Experimental arthritis is less severe in S100a9-/- mice (which lack S100A9 and S100A8/A9 proteins) and in mice receiving anti-S100A9 antibodies." (PMID 31437241, 2019). "S100A8/S100A9 acts on different cell types and induces several molecular pathways highly relevant in the pathology of arthritis." (PMID 30828327, 2019). "This study suggests that S100A8 is an anti-inflammatory DAMP that regulates myeloid cell differentiation, thereby mitigating the development of experimental arthritis." (PMID 31437241, 2019). "High extracellular concentrations of S100A8 and S100A9 are found in the serum and at inflammatory sites in autoimmune diseases including arthritis, lupus, and Crohn’s disease." (PMID 23977231, 2013). "The expression of S100A8 and S100A9 was found to be strongest at the cartilage-pannus junction, which is the prime site of cartilage destruction and bone erosion in arthritis." (PMID 19710928, 2009). "S100A8/A9 deficiency does not significantly affect inflammation and joint destruction in mice with high IL1β signaling suggesting that S100A8/A9 is not essential for the development of arthritis under these conditions." (PMID 34412663, 2021). "Furthermore, a function study reported that the S100A8 stimulation in chondrocytes induces upregulation of mRNA levels of MMP-2, MMP-3, MMP-9, and MMP-13 and ADAMTS-4 and ADAMTS-5 in experimental murine arthritis, which is similar to our findings." (PMID 31815654, 2019). "However, no direct molecular or functional link between S100A8/A9 and C/EBPδ in arthritis has yet been reported." (PMID 35543413, 2022). "S100A8/A9 and S100A12 serum levels were elevated not only in patients with active joint inflammation but also patients with inactive joint inflammation but active uveitis, indicating that this may be a systemic marker of ongoing immune response rather than a specific disease group." (PMID 34438537, 2021).
Arthritis (continued). "In the present study, we show that the absence of S100a9 does not alter joint inflammation, cartilage destruction, and bone erosion in the ankle joints of Il1rn−/− mice, suggesting that S100A8/A9 is not essential for the development of arthritis in the presence of such excessive IL-1 signaling." (PMID 34412663, 2021). "Therefore, we investigated whether joint pathology was affected by the absence of S100A8/A9 in Il1rn−/− mice later after the onset of arthritis in 20-week-old mice." (PMID 34412663, 2021). "Therefore, in our study, the septic arthritis mice may suffer from more severe systemic infection at the pre-arthritis stage compared to those infected mice without septic arthritis and high S100a8/a9 expression may just reflect a more severe systemic inflammation in those mice." (PMID 37396347, 2023).